ADAM17 (ADAM metallopeptidase domain 17)
Diseases named in the same sentence as ADAM17 in open-access papers (continued):
Sharing a sentence is not in itself a finding about the gene and the disease.
cancer (continued). "The use of bispecific proteins targeting the EGFR/ADAM17 axis could be an innovative strategy for the treatment of EGFR-dependent cancers." (PMID 32050662, 2020). "Furthermore, MICA and MICB shedding from a range of tumour cell lines was attributed to either or both ADAM10 and ADAM17, but the regulation of this process was different depending on the cancer cell lines tested." (PMID 33352921, 2020). "A review article discussed ADAM17 inhibitors for inflammation and cancer therapy." (PMID 32986377, 2020). "A correlative study using data from the cancer genome atlas found that DLBCLs with a low PD-L1 protein-to-mRNA ratio while also having higher relative expression levels of ADAM10 or ADAM17 had worse overall survival than high PD-L1 protein-to-mRNA counterparts." (PMID 32265938, 2020). "Furthermore, the antibody provides a potential anti-cancer therapeutic based on the inhibition of ADAM-17 which resulted in reduced invasion and migration of HCC1143 TNBC mammary gland epithelial cells in vitro." (PMID 32466129, 2020). "Importantly, A17pro is cross‐species reactive (i.e., mouse and human) and thus provides an advantage over human‐specific ADAM17 antibodies which cannot be evaluated for efficacy in genetically engineered mouse models of cancer." (PMID 30833304, 2019). "Taken together, our results show that the cancer-associated R177C mutation, as well as the lack of the entire pro-domain, leads to impaired ADAM17 maturation and trafficking to the cell surface." (PMID 31060243, 2019). "Since this point mutation behaved similar to an ADAM17 variant lacking the entire pro-domain, we propose a crucial function of this ~200 amino acid long pro-peptide for proper ADAM17 maturation and function in health and disease as discussed here for cancer development." (PMID 31060243, 2019). "Moreover, the involvement of ADAM17 in fundamental pathophysiologic processes such as inflammation and cancer can be envisaged." (PMID 31694340, 2019). "Although ADAM17 SMIs show anti‐cancer efficacy in numerous preclinical models, these inhibitors are highly toxic due to the non‐specific targeting of other metalloproteinases (e.g., ADAM10), thus highlighting the need for highly selective ADAM17 inhibitors with an alternate mode of action." (PMID 30833304, 2019). "Thus, ADAM17 inhibition sensitized cancer cells to cisplatin-induced apoptosis, and significantly reduced cell viability." (PMID 29662625, 2018). "In addition to ADAM17, mutations of ARID1B and CSMD1 were identified in the SS samples isolated from 3 out of 8 cancer patients in this study." (PMID 30627328, 2018). "ADAM10 and ADAM17 are even discussed as potential targets for cancer therapy." (PMID 30081852, 2018). "Dysregulated activity of A Disintegrin And Metalloproteinase 17 (ADAM17)/TNFα Converting Enzyme (TACE) is associated with inflammatory disorders, cancer progression, and neurodegenerative disease by releasing regulatory membrane-tethered proteins like TNFα, IL6R and EGFR ligands." (PMID 28879185, 2017). "How then could an ADAM17 inhibitor, which has anti-inflammatory properties, be used for cancer immunotherapy?" (PMID 29230082, 2017). "Our results suggest that therapies against ADAM10 and ADAM17 may promote cancer stem cell migration away from the tumourigenic niche resulting in a differentiated phenotype that is more susceptible to treatment." (PMID 27541285, 2017). "ADAM17 inhibition may be useful for the treatment of attenuated cancer immune surveillance and/or bone metastases." (PMID 27573075, 2016). "Moreover, blocking CD16 cleavage by inhibiting ADAM metallopeptidase domain 17 (ADAM17) to boost NK cell cytotoxicity towards cancers has been suggested by a recent study." (PMID 27356741, 2016). "Taken together, the results suggest the possibility of degradation of the ADAM17-expressing cancer cells, which may result in the inactivation of IFN-γ." (PMID 27573075, 2016). "ADAM17 promoted cancer cell proliferation through shedding EGFR ligands." (PMID 25351873, 2015).
cancer (continued). "Given that CD13 and ADAM17 are expressed in various human cancers, it may be of great value to establish the biological significance of CD13-ADAM17 association in this context." (PMID 25246708, 2014). "Our results indicate that ADAM17-directed therapies could be applicable towards a much wider panoply of cancers." (PMID 23251384, 2012). "Thus, ADAM17 makes an attractive target for development of inhibitors, which would have broad spectrum therapeutic potential in the treatment of patients with cancer." (PMID 22792380, 2012). "It remains unclear which of ADAM17 substrates expressed by MC38CEA cancer cells could trigger changes in immune response." (PMID 23251384, 2012). "Furthermore, a number of selective ADAM inhibitors, especially against ADAM10 and ADAM17, have been shown to have anti-cancer effects." (PMID 21906355, 2011). "Patients displaying a huge expression of this proteinase have a shorter overall survival than those with a low expression of ADAM-17 suggesting that ADAM-17 might be a good target to predict the outcome of cancer development." (PMID 20034386, 2009). "In addition, proteolytic depletion of phase-related tumour-protein-related protein I by ADAM17 may suppress the fatal cell-specific cytotoxicity of cancer cells." (PMID 38956273, 2024). "Moreover, it was demonstrated that suppression of ADAM17 has the potency to become a NK cell based immunotherapy in cancer via enhancing the purity of extended NK cells and increasing antibody dependent cellular cytotoxicity (ADCC) against trastuzumab in the cell lines of BC." (PMID 38317965, 2024). "In addition, ADAM17 plays a crucial role in various types of cancers." (PMID 37165578, 2023). "In addition, multiple studies have indicated that ADAM17 inhibition may represent a viable strategy for cancer treatment, making this ADAM a promising therapeutic target." (PMID 37175410, 2023). "With this in mind, the targeting of iTAP/Frmd8 may be an appealing potential strategy to target ADAM17 activity in specific compartments during chronic inflammatory diseases or cancer, while avoiding collateral impact on the vital functions of ADAM17 in normal tissues." (PMID 36720499, 2023). "In addition, the role of ADAM17 in post-translational modifications, such as proteolysis, phosphorylation, glycosylation, and post-transcriptional regulation in cancer progression remains unclear." (PMID 36466812, 2022). "The seven prevalent ‘candidate genes’ (ADAM10, ADAM17, AKT1, CTNNB1, ESR1, FGFR1, PIK3CA) showed direct associations with enriched terms under the categories of ‘Neurodegenerative disorders’, ‘Neurodevelopmental diseases’, ‘CNS tumour/cancer’ and ‘Cellular Signaling pathways’." (PMID 36229517, 2022). "The mentioned ADAM10 and ADAM17 proteases were also shown to participate in shedding soluble CD137, a member of the TNF receptor family stimulating T cell proliferation, implicated in inflammatory diseases, autoimmunity, and cancer, i.e., diseases strongly associated with aging." (PMID 35958270, 2022). "In cancer patients, it is unclear whether the expression or the activity of ADAM17 is increased." (PMID 33809851, 2021). "Therefore, we investigated whether Dis-ADAM17 could be the integrin α5β1 ligand mediating the interactions of exosomes with Colo-320 cancer cells." (PMID 34576100, 2021). "Moreover, novel evidence has emerged that ADAM17 can modulate the capability of cancer cells to evade immunosurveillance and driving cancer evasion, by regulating cleavage of crucial immune receptors and ligands in both immune and target cancer cells." (PMID 33579029, 2021). "Thus far, exogenous ADAM17 inhibitors have been trialled in the setting of cancer." (PMID 33904577, 2021). "Therefore, ADAM17 is a pivotal switch for a myriad of physiological and pathological processes including cell proliferation, regeneration, differentiation, inflammation and cancer progression." (PMID 31438559, 2019).
cancer (continued). "The synergy observed between ADAM17 and PI3K/AKT pathway inhibitors may work through independent inhibition of multiple cancer hallmarks, or via a more direct mechanism whereby inhibition of ADAM17 driven proteolysis and shedding of RTKs20 stabilizes and increases signaling through PI3K/AKT41,42." (PMID 31209238, 2019). "We decided to build on these findings by assessing whether the adhesion of several other human cell lines derived either from solid tumors (“cancer cell lines”) or hematological malignancies (“leukocytic cell lines”) to immobilized recombinant ADAM17-Fc was also mediated by integrin α5β1." (PMID 30455686, 2018). "Thus, it is tempting to speculate that one of the wide array of MDSC ecto-proteases with different structural substrate requirements from ADAM17 contribute to lymphocyte L-selectin downregulation in cancer." (PMID 27929373, 2016). "Importantly, however, this also means that ADAM17 could be a therapeutic target molecule for the inhibition of escape from cancer surveillance." (PMID 27573075, 2016). "Conversely, blocking ADAM17 through inhibitors, antibodies, or silencing techniques reduces AREG release and enhances the sensitivity of cancer cells to cisplatin’s apoptotic effects." (PMID 41050403, 2025). "Variations in angiotensin-converting enzyme 2 (ACE2), transmembrane protease serine 2, A disintegrin and metalloprotease 17 (ADAM17), and Dedicator of cytokinesis 2 (DOCK2) levels, influenced by cancer types, differ among populations." (PMID 39946554, 2025). "On the other hand, several groups have reported that TEVs produced by different cancer types carry on their surface proteolytically active ADAM10 and ADAM17." (PMID 38542421, 2024). "By implementing CRISPR technology, the ADAM17 gene was knocked out from CAR-NK cells and the results showed enhanced cytotoxicity in vitro and in vivo cancer models." (PMID 38726000, 2024). "Using this platform, they found the specific combinations of biomarkers for cancer diagnosis (MMP-9, ADAM-10, and ADAM-17) with joint entropy and programming." (PMID 36831937, 2023). "Several studies have implied the roles of a disintegrin and metalloprotease-17 (ADAM17) in CD16 shedding, which is suggested to be a potential hurdle for effective NK cell ADCC therapy, including cancer immunotherapy." (PMID 37669308, 2023). "RECK can also modulate the activity of the sheddases ADAM10 and ADAM17 which are involved in the shedding and activation of Notch, a functional link between RECK and CSCs cancer stem cells." (PMID 38139236, 2023). "We analyzed the association between clinical-pathological characteristics and the expression of NOX1, ADAM17, and MCAM mRNA in three datasets (GSE39582, The Cancer Genome Atlas, and PETACC3)." (PMID 38137406, 2023). "However, our findings on ADAM17-mediated CD16 reduction in PLWH indicate that techniques in NK cell cancer immunotherapy such as ADAM17 CRISPR knockout and ADAM17-resistant CD16 overexpression could also be translated for use as NK cell-based HIV-1 immunotherapeutics." (PMID 37669308, 2023). "To confirm cancer cells as the major source of HB-EGF and AREG release, we cocultured WT and Adam17–/– 4T1 and E0771 cells with BMDMs for 48 hours." (PMID 35998057, 2022). "ADAM17 mRNA levels were lower than HSPA5 and FURIN but higher than ACE2 and TMPRSS2 in most cancer types." (PMID 35720350, 2022). "As in other cancer cells, ectodomain shedding of L1CAM is mediated by ADAM10 and ADAM17, we investigated the expression of the soluble L1CAM ectodomain in cell culture supernatant after ADAM10/17 single and double knockdown." (PMID 36293469, 2022).
cancer (continued). "In cancer cells, TRAF6 also engages and activates proteolytic enzymes such as ADAM17/TACE and presenilin-1 (PSEN1 or PS1), which leads to the generation and release of the TGFβRI intracellular domain (TGFβRI-ICD)." (PMID 35625561, 2022). "Inhibition of ADAM17 with chemical inhibitors, anti-ADAM17 antibodies or gene silencing reduced AREG release and sensitized cancer cells to cisplatin-induced apoptosis." (PMID 36140519, 2022). "We show that ADAM17 sheds heparin-binding EGF (HB-EGF) and amphiregulin (AREG) from the cancer cell surface, leading to EGFR activation in macrophages." (PMID 35998057, 2022). "ADAM17-mediated EGFR ligand shedding promotes macrophage education and macrophage-induced cancer cell invasion." (PMID 35998057, 2022). "ADAM17 (a disintegrin and metalloproteinase 17)/TACE (a TNFα-converting enzyme) overexpressed in many cancers, including CRC, is capable of Nectin-4 cleavage under hypoxic conditions." (PMID 36553083, 2022). "We show that ADAM17-dependent shedding of HB-EGF stimulates TAM education and secretion of ELR-positive chemokines, which in turn promote cancer cell invasion." (PMID 35998057, 2022). "Next, we analyzed the expression values of ADAM17, HSPA5, TMPRSS2, FURIN, and ACE2 in different cancers and corresponding normal individuals." (PMID 35720350, 2022). "ADAM17 activity correlates with a poor prognosis and worse therapy outcome in NSCLC, which makes ADAM17 a promising target for cancer treatment in combination with irradiation." (PMID 36860547, 2021). "For example, ADAM17 is activated by VEGF-A and plays a crucial role in pathological neovascularization, a key feature of cancer." (PMID 33579029, 2021). "In agreement, genetical ablation of ADAM17 on circulating NK cells by CRISPR/CAS9 led to their improved activity, with augmented cytokine production and cancer cell cytotoxicity compared to wild type controls." (PMID 33579029, 2021). "A number of studies have revealed that ADAM17 is activated by MAPKs, including the p38/MAPK signaling in both epithelial cells and cancer cells." (PMID 34746310, 2021). "In agreement with this, ADAM17 inhibitors such as ZLDI-8 were shown to prevent EMT in HCC cells by decreasing the release of Notch NICD, thereby improving the effects of anti-cancer drugs." (PMID 33805340, 2021). "Thus, for the first time, differences in the levels of 20S proteasomes, ADAM10+/ADAM17-, MMP9+ and MMP9+/MMP2+/EMMPRIN+ in plasma exosomes subpopulations between CPPs and CRCPs were revealed, thereby indicating the feasibility of using them to predict cancer risk." (PMID 33773551, 2021). "In the context of cancer, ADAM-10 and ADAM-17 have been indicated to be the principle proteases for EGFR ligands." (PMID 32948029, 2020). "The significance of an ADAM17-EGFR axis in mammary gland development and cancer has previously been described." (PMID 33208158, 2020). "This seems to be contradictory to the basic understanding of ADAM17-mediated cancer development, where increased EGF-R activity and thus tumorigenesis has been thought to be facilitated by enhanced shedding of EGF-R ligands by ADAM17." (PMID 31060243, 2019). "In our study, we analyzed serum levels of ADAM10, ADAM12, ADAM17, and ADAM28 in CRC patients, depending on clinical parameters to determine the potential role of adamalysines as a cancer biomarker." (PMID 31565100, 2019). "Malignant ascites-released membrane vesicles contain diverse activated proteases including MMP2, MMP9, uPA and ADAM17/TACE, together promoting ECM degradation and enhancing cancer cell invasiveness and metastasis." (PMID 28929459, 2018). "After the proteolytic cleavage by ADAM17, N-terminal soluble form of Jagged-1 is produced by ECs to bind and activate the receptor Notch on CRC cells to promote cancer stemness." (PMID 29435158, 2018). "Considering the importance of ADAM-10, ADAM-17, and ADAM-28 in cancer progression, we detected their expression in HC by immunohistochemistry." (PMID 29776401, 2018).
cancer (continued). "In addition, ADAM-17 has been shown to cleave the interleukin-6 receptor (IL-6R) resulting in the shedding of soluble interleukin-6 (sIL-6) which is a prerequisite for the pathogenesis of interleukin 6 (IL-6) trans-signaling effecting multiple cellular functions related to cancer and inflammation." (PMID 29393911, 2018). "Second, membrane vesicles from malignant ascites were also found to contain the activated proteases: matrix metalloproteinase (MMP)-2, MMP-9, uPA, and ADAM17/TACE." (PMID 28275576, 2017). "A disintegrin and metalloprotease domain-containing protein 17 (ADAM17), also known as TNF-alpha converting enzyme (TACE) has emerged as a potential therapeutic target in CRC and other cancers." (PMID 29029414, 2017). "Metalloproteinase ADAM17 and MT1-MMP have been identified to shed Sema4D from the surface of platelets and cancer cells." (PMID 23741311, 2013). "A specific human ADAM17 inhibitory antibody, D1(A12), has recently been developed, which inhibits the proteolysis of ADAM17 substrates (TNF-α, AREG, etc.,) in cancer cells in vitro." (PMID 22792380, 2012). "The overexpression of ADAM8, ADAM9, ADAM10, ADAM12, ADAM15, ADAM17, and ADAM28 are reported from various cancers." (PMID 22272227, 2012). "Although ADAM17 is considered a hot target for the treatment of cancer and inflammatory diseases, no ADAM17 inhibitors have yet reached the market." (PMID 39292373, 2025). "In cancer, ADAM10 and ADAM17 have been the most actively studied." (PMID 39286024, 2024). "Finally, the regulatory mechanism of CD122 by ADAM17 was verified in human CD8+ T cells, highlighting the potential application in cancer immunotherapy." (PMID 38918390, 2024). "L1CAM-mediated cancer progression can be induced by proteolytic cleavage-products of full-length L1CAM (L1CAM-FL) by family members of a disintegrin and metalloproteinase (ADAM) such as ADAM10 and ADAM17." (PMID 38263290, 2024). "By inhibiting ADAM17 alongside TriKE treatment, researchers aim to enhance the therapeutic effects of TriKEs while concurrently upregulating IFN-γ, a critical player in the anti-cancer immune response." (PMID 38745768, 2024). "Specifically, ADAM10 regulates constitutive LAG3 cleavage, while ADAM17 regulates LAG3 cleavage induced by T cell receptor signaling, where ADAM17 showed immune and SARS-CoV-2 entry for the expression in patients with cancer." (PMID 39211038, 2024). "In addition, we demonstrate that NOX1, ADAM17, and membrane MCAM are present in a multiprotein complex in endothelial and cancer cells and that long-term treatment with NOX1 inhibitor partially decreases ADAM17 expression and the generation of sMCAM." (PMID 38137406, 2023). "The cleavage of CD16 by ADAM17 leads to a decrease of CD16 binding avidity to antibody-coated target cells and in turn can suppress NK cells antitumor activity through ADCC, allowing cancer cells to create an immunosuppressive TME." (PMID 38077389, 2023). "The participants constitute over 15% of the adult population of Iceland, and the timing of the sample collection, regarding cancer onset, diagnosis and progression, is unlikely to have a major impact on the GWAS of ADAM17." (PMID 37958866, 2023). "Conclusively we advocate that foremost combined treatment strategies together with radiotherapy (e.g. with anti-ADAM17 agents), rather than monotherapies will advance our collective battle against cancer." (PMID 36998455, 2023). "In previous reports, Akt activation was found to increase the activity of A Disintegrin and Metalloproteinase 17 (ADAM17), which increases the shedding of heparin-binding EGF (HB-EGF) and amphiregulin (AREG) from the cancer cell surface, leading to EGFR activation." (PMID 37779142, 2023). "Additionally, RNA-Seq and ELISA experiments revealed that ADAM17-dependent HB-EGF ligand release induced the expression and secretion of CXCL chemokines in macrophages, which in turn stimulated cancer cell invasion." (PMID 35998057, 2022).